CSNK1A1P1 (casein kinase 1 alpha 1 pseudogene 1)
Synonyms: formerly CSNK1A1P
Gene: Transcribed processed pseudogene on chromosome 15 (36,817,133 to 36,818,113, reverse strand). Ensembl gene ENSG00000223518.
Diseases named in the same sentence as CSNK1A1P1 in open-access papers:
CSNK1A1P1 is named in the same sentence as 3 diseases in open-access papers, as found by Europe PMC text mining. Sharing a sentence is not in itself a finding about the gene and the disease. The quoted sentences say what the papers report.
astrocytoma (1 paper, 2024). "Located in the 15q14 region, CSNK1A1P1 has been linked to astrocytoma, as reported by25." (PMID 39550379, 2024).
melanoma (1 paper, 2021). A malignant, usually aggressive tumor composed of atypical, neoplastic melanocytes. "On the other hand CYT-low metastatic melanomas had recurrent amplifications in loci 5p15.33 (TERT), 6p25.1 (CDYL), 7p22.2 (RAC1), 12q15 (MDM1) and recurrent deletions in 5q31.2 (CTNNA1, FGF1), 11q22.3 (FDX1, RDX, ZC3H12C), and 15q14 (RASGRP1, CSNK1A1P1, SPRED1)." (PMID 33779796, 2021).
CSNK1A1P1 also shares sentences with these, for which no sentence is quoted: Tumor (1 paper).